ENSG00000277968
Gene: Miscellaneous RNA gene on chromosome 5 (142,317,830 to 142,317,920, forward strand). Ensembl gene ENSG00000277968.
Gene Ontology:
Cellular component: cytoplasm